MTUS1 (microtubule associated scaffold protein 1)
Diseases named in the same sentence as MTUS1 in open-access papers (continued):
Sharing a sentence is not in itself a finding about the gene and the disease.
tumor (continued). "In conclusion, our study demonstrated that down-regulation of selected mitochondrial TS genes such as SIRT3, SIRT4 and MTUS1 in HNSCC indicate aggressive tumor behaviors and may predict an unfavorable clinical outcome." (PMID 26785117, 2016). "In the papillary bladder cancer group MTUS1 expression was lost in 50.6% of the tumours (43/85)." (PMID 24650297, 2014). "Most tumors have their origin in endothelial and epithelial cells, thus the localisation of MTUS1 could be a hint of its function as tumor suppressor gene." (PMID 22200760, 2012). "In HGG, higher MTUS1/ATIP1 expression might interfere with tumor irradiation therapy." (PMID 33809019, 2021). "The previously identified genes, MTUS1 and COL3A1, wherein carriers of MTUS1 frameshift insertion associated with a significant difference in gene expression and OS, and COL3A1 gene expression correlated with tumor aggressiveness, were also included in the selection." (PMID 31533654, 2019). "These genes include three tumour suppressors (DMBT1, MTUS1, and KLRC1), two genes involved with cell communication and myelin (GJB1 and KLK6), and a P450 monooxygenase involved in the synthesis of cholesterol and lipids (CYP4F12)." (PMID 37628980, 2023). "These correlations suggested that MTUS1 can recruit immune T, Th1, Th2, Tcm, T helper, CD4+ T, and CD8+ T cells into the tumour microenvironment and prevent the recruitment of Treg cells that promote immune tolerance and angiogenesis." (PMID 35962436, 2022). "Previous studies have reported that the interaction between the lncRNA LIFR-AS1 and MTUS1 can block the MEK/ERK pathway, thereby inhibiting tumour cell proliferation, migration, and invasion." (PMID 35962436, 2022). "MTUS1/ATIP1 has been reported as a TSG in a variety of cancers as it inhibits ERK phosphorylation, proliferation, tumor cell motility and metastasis." (PMID 33809019, 2021). "In summary, our data identified a tumor-suppressor role of SOBRBS2 and unveiled that SOBRBS2, as an RBP, upregulated downstream target MTUS1 expression by binding to its mRNA 3′UTR." (PMID 33311452, 2020). "In the multivariate analysis, copy-number losses (CNLs) in chromosome B1 (1–23 Mb) harbouring several tumour-repressors (e.g. CSMD1, MTUS1, MSR1, DBC2, and TUSC3) negatively influenced DFS." (PMID 31969654, 2020). "On the other hand, common CNLs negatively influencing survival intervals harboured important tumour suppressors (e.g. CSMD1, MTUS1, MSR1, DBC2, and TUSC3) and genes enriching biological processes that would normally prevent cellular movement." (PMID 31969654, 2020). "For example, the MTUS1 and SFRP1 genes on chromosome 8p22 and 8p12-11.1 loci have been identified for their tumor suppression function in UBUC." (PMID 26307680, 2015). "The down-regulation of the MTUS1 gene has been documented in many cancer types; among the 5 isoforms, ATIP1 and ATIP3a/b have been found to exhibit tumor suppressor function." (PMID 25885343, 2015). "As a mitochondrial tumor suppressor gene, MTUS1/ATIP1 had not been verified to localize at mitochondria." (PMID 38725862, 2024). "MTUS1 expression was not an independent prognostic factor in multivariable Cox regression analysis, whereas tumor size and lymphovascular invasion were independent prognostic factors for both DFS and CSS, and AJCC stage for CSS only." (PMID 34359333, 2021). "On the other hand, CNLs in FCA B1 1–23 Mb (human homologue region located in HSA 8p) were significant in multivariate analysis and harboured multiple tumour suppressors (e.g. CSMD1, MSR1, MTUS1, and TUSC3) previously correlated with poor prognosis in HBCs15,19,23,27,70." (PMID 31969654, 2020). "In conclusion, down-regulation of expression of certain mitochondrial tumor-suppressor genes, such as SIRT3, SIRT4, and MTUS1, in HNSCC cells indicates aggressive tumor behaviors, and may predict an unfavorable clinical outcome." (PMID 33585187, 2020).
tumor (continued). "Our findings regarding papillary tumours make it very likely that MTUS1 does not act as a classical tumour suppressor and make a role as new potential progression marker in papillary bladder cancer very unlikely." (PMID 24650297, 2014). "Furthermore, the relationship between the expression of MTUS1 and tumour-infiltrating immune cells has not been previously reported." (PMID 35962436, 2022). "The expression of MTUS1 was significantly decreased in CRC tissues compared to normal tissues, according to the results based on clinicopathological factors, including sex, age, pathologic stage, T stage, N stage, M stage, CEA level, neoplasm type, and survival status." (PMID 35962436, 2022). "Within this region, there are established tumor suppressors (DLC1, DOK2 and LZTS1), as well as potential tumor suppressor genes (CSMD1, MTUS1, and MSR1), and many other genes not established in cancers." (PMID 35994499, 2022).
cancer (31 papers, 2009 to 2025). A tumor composed of atypical neoplastic, often pleomorphic cells that invade other tissues. "The metastatic dissemination of the primary disease is responsible for most cancer-associated mortality, which would explain why low expression of MTUS1 can lead to a poor prognosis in CRC patients." (PMID 35962436, 2022). "Epigenetic mechanisms underlying MTUS1 down-regulation in various cancers include promoter methylation and regulation of ATIP mRNA turnover and stability by RNA binding proteins, long non-coding RNA and microRNAs." (PMID 34062782, 2021). "The expression of the microtubule-associated tumor suppressor (MTUS1) gene has been reported to be lost in various cancer types like colon, ovarian, pancreas, bladder, gastric and lung cancer." (PMID 33809019, 2021). "Down regulation of MTUS1 gene has been implicated in a wide range of cancers as well as various human diseases." (PMID 34125870, 2021). "So, both upregulation and downregulation of MTUS1 can lead to cancer progression though the molecular mechanisms underlying this process is still uncharted and can be a new agenda of research." (PMID 34125870, 2021). "Microtubule-associated tumor suppressor gene (MTUS1) has been identified as tumor suppressor gene in many malignant tumors." (PMID 25885343, 2015). "ATIP3 is a novel MAP encoded by candidate tumor suppressor gene MTUS1 whose expression is markedly down-regulated in a variety of human cancers." (PMID 26498358, 2015). "Survival, however, was only influenced in advanced carcinomas, where loss of MTUS1 was associated with adverse OS and DSS." (PMID 24650297, 2014). "MTUS1 is thought to be downregulated in various human cancers and associated with poor prognosis." (PMID 36980447, 2023). "By providing a molecular and functional analysis of ATIP3, the present study brings a major contribution to the characterization of MTUS1 gene products and to the identification of potential driver mutations that may lead to a loss of function of the ATIP3 protein in cancer." (PMID 19794912, 2009). "Decreased expression of these proteins, including MTUS1, was observed in patients with advanced stages of cancers, such as T3 and T4." (PMID 37627097, 2023). "The association between cancer and several other mitochondrial-related proteins, such as silent information regulator 3 (SIRT3), mitochondrial tumor suppressor gene 1 (MTUS1), and 8-hydroxyguanine DNA glycosylase (OGG1), has been reported." (PMID 37627097, 2023). "We found that the proteins interacting with MTUS1 were involved in multiple pathways related to cancer development." (PMID 35962436, 2022). "For example, the Microtubule-associated tumor suppressor gene (MTUS1) was found to be downregulated in OTSCC and various other cancer types and was associated with decreased overall survival." (PMID 35600372, 2022). "GO and KEGG enrichment analyses showed that MTUS1 was involved in multiple cancer-related signalling pathways." (PMID 35962436, 2022). "This revealed that most of the cancers occurred due to the downregulation of MTUS1 though some of them resulted from upregulation of MTUS1." (PMID 34125870, 2021). "The ATIP1 and ATIP3 splice variant of MTUS1-encoded proteins have been reported to interfere with ERK signaling, inducing apoptosis in cancer cells." (PMID 34359333, 2021). "In several other cancer types, including breast, colorectal, lung, gallbladder cancer, and osteosarcoma, microRNAs also down-regulate MTUS1 expression." (PMID 34062782, 2021). "Patients with low MTUS1 expression also showed shorter disease-free survival (p = 0.002) and cancer-specific survival (p = 0.006)." (PMID 34359333, 2021). "Of interest, the MTUS1 gene was also described as an interesting prognostic biomarker of patient clinical outcome in other cancer types." (PMID 34062782, 2021). "MTUS1 was discovered as a potential tumor suppressor gene, and downregulation of MTUS1 has been confirmed in several types of human cancers." (PMID 34359333, 2021).
cancer (continued). "Despite the impact of MTUS1 has been annotated in the cell proliferation of several carcinomas, the in silico analysis of deleterious nsSNPs in our candidate MTUS1 gene has remained uncharacterized yet." (PMID 34125870, 2021). "All these strongly suggested that FLH2 plays a role in the regulation of the neovascularization of the cancer through regulating MTUS1." (PMID 26603105, 2015). "The MTUS1/ATIP expression was significantly decreased in primary cancer tissues compared with normal salivary gland tissues." (PMID 25885343, 2015). "ATIP is also named mitochondrial tumor suppressor gene 1 (MTUS1), which shows mutation or copy number variants in human malignant tumors." (PMID 23565185, 2013). "Previously, MTUS1 has been reported to play a role in the cell proliferation as well as in cancer development." (PMID 22200760, 2012). "As a pre-requisite to functional studies, a panel of human cancer cell lines was analyzed for MTUS1 expression by real-time RT-PCR." (PMID 19794912, 2009). "Previous studies have reported that MTUS1 expression levels are reduced in cancers from pancreas, colon, ovary and head-and-neck." (PMID 19794912, 2009). "Previous studies have shown that MTUS1 expression levels are reduced in cancers from pancreas, ovary, colon and head-and-neck." (PMID 19794912, 2009). "Furthermore, this study revealed that knockdown of MTUS1 reversed the regulatory effect of PRR7-AS1 and RNF2 on OS cells behaviors, validating the anti-cancer role of MTUS1 in OS." (PMID 38033505, 2023). "Furthermore, the functional effect and prognostic value of low MTUS1 expression in other cancers were successively confirmed." (PMID 35962436, 2022). "Downregulation of MTUS1 has been previously reported in various cancers, including CRC." (PMID 35962436, 2022). "Furthermore, we used the TIMER database to examine which cancers have differences in MTUS1 mRNA expression levels." (PMID 35962436, 2022). "The HIF-1 pathway mediates cell proliferation and apoptosis, which might explain why high MTUS1 expression is correlated with a better prognosis in cancer patients." (PMID 35962436, 2022). "Furthermore, patients with decreased MTUS1 expression showed worse disease-free and cancer-specific survival." (PMID 34359333, 2021). "Downregulation of MTUS1 has been demonstrated in various human cancers, including pancreatic, ovarian, head and neck, colorectal, breast, bladder, stomach, lung, gallbladder, and kidney (renal cell carcinoma) cancers." (PMID 34359333, 2021). "MTUS1 modulation by miR-19a/b may explain why miR-19a/b upregulation and MTUS1 downregulation during lung carcinogenesis promote cancer progression." (PMID 28364280, 2017). "To date, several new candidate cancer-susceptible genes have been cloned to 8p22, such as deleted in breast cancer 2 (DBC2), leucine zipper tumor suppressor 1 (LZTS1), deleted in liver cancer 1 (DLC1), and mitochondrial tumor suppressor 1 (MTUS1)." (PMID 22028972, 2012). "Moreover, the expression of MTUS1 is decreased in different human cancers, including CRC." (PMID 35962436, 2022). "Therefore, the main purpose of the study was to prove that MTUS1 can regulate the cell proliferation and to investigate if the lack of MTUS1 alone can cause cancer development or major pathological changes." (PMID 22200760, 2012). "To represent the opposite expression of MTUS1 gene more clearly, we performed box plot analysis of MTUS1 gene expression in STAD and UCEC where these cancers resulted from upregulation and downregulation of MTUS1 accordingly." (PMID 34125870, 2021). "As for primary tumors, ATIP3 expression in cancer cells paralleled that of total MTUS1 mRNA, while ATIP1 remained undetectable in every cell line examined." (PMID 19794912, 2009).
cancer (continued). "In agreement with our RT-PCR studies, western blot experiments using anti-MTUS1 antibodies revealed a polypeptide of 170 KDa corresponding to ATIP3 in cancer cell lines MDA-MB-468 and SK-MES, but not in MCF7 nor MDA-MB-231." (PMID 19794912, 2009). "However, the level of MTUS1 expression at different points of cancer progression has not yet been specified." (PMID 34359333, 2021).
cardiovascular disease (2 papers, 2012 to 2022). "By searching for the potential targets of miR-877-3p, we found that among the potential targets regulated by miR-877-3p, GADD45g, NSUN2, YTHDF2 and MTUS1 have regulatory roles in the involvement of cardiovascular disease 30-32." (PMID 35928721, 2022).
neurological disease (2 papers, 2012 to 2023). "Three target genes (CNIH4, MTUS1, and FES) were enriched in neurological disease-related network." (PMID 38092781, 2023).
heart disease (1 paper, 2025). "The literature lacks human studies on the specific effects of the MTUS1 gene in heart disease." (PMID 40004439, 2025). "However, the literature lacks human studies on the specific effects of the MTUS1 gene in heart disease, particularly in congenital LVNC." (PMID 40004439, 2025).
neoplastic disorder (1 paper, 2023). "The CFA16 region contains genes that may influence cardiac and neoplastic disorder risk including microtubule-associated tumor suppressor 1 (MTUS1) and fibrinogen-like protein 1 (FGL1)." (PMID 37277858, 2023).
MTUS1 also shares sentences with these, for which no sentence is quoted: oral squamous cell carcinoma (3 papers); multiple myeloma (2); type II diabetes (2); uveal melanoma (2); adenoid cystic carcinoma of the salivary gland (1); advanced heart failure (1); atherosclerosis (1); benign prostatic hyperplasia (1); endothelial dysfunction (1); gallbladder adenocarcinoma (1); gallbladder carcinoma (1); glioblastoma (1); glioma (1); Insulin resistance (1); kidney cancer (1); Left ventricular noncompaction cardiomyopathy (1); leukocytosis (1); mental retardation (1); mesothelioma (1); metabolic disorders (1); myeloid neoplasm (1); nephritis (1); non-small cell lung carcinoma (1); Obesity (1); osteosarcoma (1); pilocytic astrocytoma (1); prostatic intraepithelial neoplasia (1); renal cell carcinoma (1); sarcoma (1); schizophrenia (1).
A further 3 diseases each share a sentence with MTUS1 in 1 paper.